INS (insulin)
Diseases named in the same sentence as INS in open-access papers (continued):
Sharing a sentence is not in itself a finding about the gene and the disease.
Hypoglycemia (continued). "Therefore, it is important to directly query patients treated with an insulin secretagogue or with insulin about episodes of hypoglycemia at every medical examination." (PMID 34572493, 2021). "They argued that insulin is a growth factor and both insulin and hypoglycemia stimulate appetite and this may have influenced the effect on the GWG." (PMID 34976684, 2021). "However, in contrast to findings in GSD Ia, acute hypoglycemia during an insulin stress test in humans increases platelet aggregation in response to ADP without affecting platelet ATP and ADP content." (PMID 34091064, 2021). "The project has been continued by Eli Lilly, a U.S. pharmaceutical company that obtained registration for IN glucagon as a powder (with beta-cyclodextrin plus dodecyl-phospho-choline as the promoter) for severe hypoglycemia in adult and adolescent insulin users in US, Canada, and Europe in 2019." (PMID 34638984, 2021). "Therefore, strategies for enhancing knowledge about hypoglycemia and insulin use in patients with T2DM need to be developed." (PMID 34497858, 2021). "In the case of patients with COVID-19, one should not avoid insulin therapy despite the fact that it is tied to hypoglycemia risk." (PMID 33801468, 2021). "Low-affinity autoantibodies against insulin may influence the levels of bioavailable insulin with potential effects on hypoglycemia." (PMID 33953692, 2021). "However, preserved beta-cell mass allows for normal insulin secretion and glucose tolerance, with enhanced glucagon release in response to hypoglycemia." (PMID 33619692, 2021). "The fear of hypoglycemia is the principal factor associated with their nonadherence to insulin therapy." (PMID 34690922, 2021). "Hypoglycemia was the most frequent adverse drug event of oral antidiabetics and insulin." (PMID 34449695, 2021). "We measured plasma copeptin in response to insulin-induced hypoglycemia." (PMID 34787082, 2021). "However, the precise dosing of insulin required to match body metabolism is highly challenging, often resulting in either hyperglycemia or hypoglycemia." (PMID 34027090, 2021). "Cardiac arrhythmias were common in insulin-treated patients with T2D and were associated with glycemic variability, whereas arrhythmias were not strongly associated with hypoglycemia." (PMID 34952579, 2021). "Consequently, islet transplantation is only available to patients who are suffering from hypoglycemia unawareness or with serious hypoglycemia condition which cannot be controlled using conventional insulin therapy." (PMID 33802091, 2021). "The authors concluded that 30% additional insulin, delivered via combination bolus, results in improved postprandial blood glucose without an increased risk of hypoglycaemia." (PMID 34684559, 2021). "3.Consider changes in insulin dose only after thorough evaluation and discussion to rule out preventable causes of hypoglycaemia." (PMID 33098260, 2021). "In contrast, the catecholamine adrenaline is a body’s soluble signal that has a clear differential effect on two major islet cells subpopulations: it inhibits secretion of insulin by β-cells and induces secretion of glucagon from α-cells to rescue extreme hypoglycemia." (PMID 34460580, 2021). "Thus, insulin therapy remains one of the pillars in controlling glucose metabolism alterations in burns, but needs appropriate monitoring of glycemia, hypoglycemia being the main drawback in IIT in burns." (PMID 34068151, 2021). "The peptide hormone is detectable in the CSF for at least 80 min, and less than 3% of the administered insulin reaches the systemic bloodstream without causing systemic hypoglycemia or hepatic first-pass metabolism." (PMID 33799976, 2021). "Furthermore, twice-daily basal insulin treatment showed better glycemic control with a lower risk of hypoglycemia than both twice-daily neutral protamine Hagedorn (NPH) and once-daily basal insulin treatments." (PMID 34564455, 2021).
Hypoglycemia (continued). "The greatest risks may be hypoglycemia or hypotension due to delays in stopping or reducing anti-hypertensive agents, insulin, and insulin secretagogues." (PMID 34350205, 2021). "After treatment of diabetic ketoacidosis with insulin, they responded to sulfonylurea (glibenclamide) treatment, but were switched to repaglinide because of blood sugar fluctuations in terms of hyper- and hypoglycemia." (PMID 34696808, 2021). "Positive trends were observed for hypoglycemia and insulin dose." (PMID 33908894, 2021). "In the insulin-induced hypoglycemia provocative test, her GH peaked at 4.99 ng/mL." (PMID 34220717, 2021). "Dapagliflozin add-on to insulin therapy leads to a reduction in insulin dose and weight loss, without any increases in hypoglycemia in T1D." (PMID 34497852, 2021). "One of the consequences of this is the fact that most AP systems are rather conservative in insulin delivery to avoid overdoses of insulin, which may lead to hypoglycemia." (PMID 34770425, 2021). "Insulin-induced hypoglycemia has been demonstrated to prolong the corrected QT (QTc) interval." (PMID 33898141, 2021). "Another potential adverse effect of intensive insulin therapy, hypoglycemia, may also result in excessive carbohydrate consumption to either treat or prevent low blood sugars, further adding to weight gain." (PMID 33828529, 2021). "Hypoglycemia is a serious side effect of anti-diabetic drugs that promote insulin secretion." (PMID 33804798, 2021). "The median time of insulin was 12 months (range 0.07–78) before the onset of hypoglycemia." (PMID 33827670, 2021). "Furthermore, findings show that individuals with good fitness level seem to be more prone to exercise-induced hypoglycemia because of their higher insulin sensitivity." (PMID 33770092, 2021). "Thus, IDegAsp was more effective than conventional premixed insulin and basal insulin at reducing blood glucose with fewer nocturnal hypoglycemia events." (PMID 34564455, 2021). "In this setting, hypoglycemia might be exacerbated by the fact that diabetic patients probably consume smaller amounts of calories during lunch, despite receiving the prescribed insulin or medication doses." (PMID 33418926, 2021). "Technological advances in insulin production (e.g., analogues), insulin delivery devices (e.g., insulin pumps) and glucose monitoring devices have contributed to overall metabolic improvement, but in clinical practice, severe hypoglycemia rates, especially in pregnant women, remain high." (PMID 34959363, 2021). "Patients with GFR <20 mL/min present a decrease in the hepatic metabolism of insulin, a condition worsened by the action of uremic toxins on the liver, thus requiring a reduced exogenous insulin dose according to their renal impairment, in order to avoid hypoglycemia." (PMID 34062938, 2021). "Insulin-induced hypoglycemia shifts 18F-FDG from the original area to insulin-sensitive organs." (PMID 33795778, 2021). "Additionally, the reduction of HbA1c and fasting plasma glucose, and the occurrence of hypoglycemia, were comparable between sitagliptin and insulin glargine when added-on to metformin." (PMID 33808901, 2021). "Insulin works as an anabolic hormone responsible for weight gain and neonatal hypoglycemia." (PMID 33513843, 2021). "Moreover, in humans, tissue glucose concentration nadirs in muscle have been reported to be delayed in time and lower in magnitude relative to glucose concentrations in adipose tissue and blood, especially during insulin-induced hypoglycemia." (PMID 33562672, 2021). "Work with patients to ensure they are familiar with the different pens/devices where this is a concern in case of switching between different insulin glargine preparations (and other long-acting insulin biosimilars when they become available) to minimise the potential for hypoglycaemia." (PMID 34249838, 2021). "In the present study, fear of hypoglycemia had occurred following insulin injection." (PMID 33461565, 2021).
Hypoglycemia (continued). "This cohort study investigates whether serious hypoglycemia is reduced in a Medicaid population receiving calcium-channel blockers with insulin secretagogues." (PMID 34473261, 2021). "Calcium-channel blockers used concomitantly with insulin secretagogues were associated with reduced rates of serious hypoglycemia compared with the use of insulin secretagogues without CCBs." (PMID 34473261, 2021). "However, since GLP-1RA mainly lower blood glucose by stimulating glucose-dependent insulin secretion, hypoglycemia is an infrequent problem." (PMID 34305810, 2021). "A rather high insulin dose was applied to induce hypoglycemia within a short period." (PMID 34085953, 2021). "Inactivation mutation in KCNJ11 gene can lead to continuous closure of KATP channel, continuous depolarization of β cell membrane, continuous inflow of extracellular Ca2+, excessive secretion and release of insulin, resulting in congenital hyperinsulinism hypoglycemia." (PMID 34465386, 2021). "The BMI ≥ 35 kg/m2 group had a higher total daily insulin dose (59.9 ± 49.3 vs 37.2 ± 26.0, p = 0.004) and a higher rate of lipohypertrophy (5.3% vs 2.0%, p = 0.019), but suffered from less documented hypoglycaemia (21% vs 30%, p = 0.007)." (PMID 33757476, 2021). "Moreover, the fall in blood glucose during prolonged exercise is accompanied by a reduction in insulin and a rise in glucagon concentrations, particularly if a degree of hypoglycemia ensues." (PMID 34284060, 2021). "In summary, in the present study, we uncovered some of the mechanisms by which the brain responds to different glycemic situations, providing experimental evidence that insulin-induced recurrent hypoglycemia has the capacity to evoke adaptive responses in the brain cortex." (PMID 34948265, 2021). "SGLT2 inhibitors are an insulin-independent mechanism, producing a therapeutic effect by increasing the excretion of urinary glucose without causing hypoglycemia." (PMID 33808901, 2021). "In short, new antidiabetic drugs combined with basal insulin or metformin might be preferred pharmacological strategies for reducing hypoglycemia and oxidative stress, thus decreasing the incidence of diabetic complications." (PMID 33413392, 2021). "A disorder rarely reported in the West, IAS may be first suspected in the context of spontaneous hypoglycemia when a high insulin concentration and increased insulin/C-peptide molar ratio is identified." (PMID 34051096, 2021). "However, attention must be paid to some potentially serious adverse events, such as hypoglycemia (when combined with insulin or insulin secretagogues), lower limb ischemia, and diabetic ketoacidosis." (PMID 34068655, 2021). "Finally, careful studies, such as those first done to establish the guideline of 15–20 g of CHO, should be conducted to inform CHO treatment of hypoglycemia when preceded by an insulin suspension in the era of modern insulin delivery systems." (PMID 33535013, 2021). "In this retrospective cohort study, insulin use in people with T2DM and compensated cirrhosis was associated with higher risks of hypoglycemia, cardiovascular events, liver-related complications, and mortality than insulin nonusers." (PMID 34118892, 2021). "The normal, unsuppressed levels of insulin, inappropriately observed in hypoglycemic neonates, further support the role of altered regulation of insulin secretion as an important contributor to postnatal hypoglycemia." (PMID 34676825, 2021). "After 4 weeks of a HFHF diet, our canine model presented a reduction in insulin sensitivity during a hyperglycemic hyperinsulinemic clamp, and it was unclear if this translated into a change in the counterregulatory response to hypoglycemia." (PMID 33769710, 2021). "The incidence of hypoglycaemia in patients with T2DM initiating basal insulin is relatively low." (PMID 33098260, 2021).
Hypoglycemia (continued). "This rise in FABP4, which correlates with the drop in blood glucose observed within the first day of life, may indicate an additional hormonal signal in the complex insulin counterregulatory endocrine network, aiming at preventing postnatal hypoglycemia." (PMID 34676825, 2021). "In T1D patients, dasiglucagon restored euglycemia after insulin-induced hypoglycemia at doses from 0.1 to 1.0 mg, and provided rapid and effective reversal of hypoglycemia in adults with T1D, with safety and tolerability similar to those reported for reconstituted glucagon injection." (PMID 34638984, 2021). "Furthermore, hypoglycemia is among the most common adverse effects of insulin treatment, especially in the context of intensive care." (PMID 34367067, 2021). "Fear of hypoglycaemia is common and associated with discontinuation of insulin therapy even in patients who have not actually experienced hypoglycaemia." (PMID 33098260, 2021). "In summary, SGLT2is as adjunctive therapy improved glycemic control and body weight and decreased the required dose of insulin without increasing the risk of hypoglycemia." (PMID 33651228, 2021). "Insulin-induced hypoglycemia is a major treatment barrier in type-1 diabetes (T1D)." (PMID 34787082, 2021). "In a study comparing the Cambridge closed-loop system using diluted insulin with the same closed-loop system using standard-strength insulin in children aged 2–7 years old, time in target glucose range was >70% and time in hypoglycaemia was <5% during both interventions." (PMID 33550442, 2021). "In addition, glucagon response to insulin‐induced hypoglycemia is impaired soon after the development of T1D, presenting further challenges to maintain tight glucose control." (PMID 34027090, 2021). "Compared to insulin therapy, 57 and 30 patients would need to be treated with a GLP-1RA over a mean of 2.3 years to prevent one case of all-cause mortality and hospitalized hypoglycemia, respectively." (PMID 33468131, 2021). "The lack of a satisfactory glycaemic control may move to increase insulin dosage thereby inducing hypoglycaemia and glycaemic variability." (PMID 33466656, 2021). "A possible drawback of the use of fast-acting insulin could be the iatrogenic induction of hypoglycemia." (PMID 33807619, 2021). "Insulin dose and carbohydrate intake changes may be needed to prevent exercise‐related hypoglycaemia." (PMID 33098260, 2021). "Other data suggest that the α cell response to hypoglycemia is dependent on pancreatic innervation, and that hepatic glucose production depends on liver innervation during insulin‐induced hypoglycemia." (PMID 33769710, 2021). "The child using pre-meal regular insulin may experience hypoglycemia after 2–3 h and would benefit from a mid-meal, portioned, moderate carbohydrate snack like fruit or a pulse-based snack (roasted or boiled pulse, pulse pancake etc.)." (PMID 34959978, 2021). "However, insulin-induced hypoglycemia was worsened, suggesting that the effects of serotonin are glucose-independent." (PMID 34659118, 2021). "A key benefit of CGM use in insulin-treated T2D is the ability to program alerts for hypoglycaemia." (PMID 33950566, 2021). "These arrhythmias could be related to abnormal cardiac repolarization observed in spontaneous and experimental hypoglycaemia studies, where hypoglycaemia was induced by an infusion of insulin." (PMID 34814734, 2021). "This is in line with the latest treatment guidelines in decompensated diabetic children, in which a decrease of insulin dose of < 0.05 to 0.1 unit/kg/h is only recommended after DKA has resolved or hypoglycemia is impending, despite the use of 10% or even 12.5% glucose solutions." (PMID 33945208, 2021). "This insulin effect may also explain the reduced 18F-FDG accumulation in insulin-insensitive organs with insulin-induced hypoglycemia." (PMID 33795778, 2021).
Hypoglycemia (continued). "We further report that these mice exhibit a colony average higher body weight, lower blood glucose, and elevated plasma insulin levels but there was a significant sex interaction effect with the relative hypoglycemia and hyperinsulinemia more apparent in males than females." (PMID 33430405, 2021). "Monitoring alcohol concentrations in real time may allow improved insulin delivery protocols to reduce delayed hypoglycemia." (PMID 34027090, 2021). "AVP deficient Brattleboro rats have a blunted corticosterone response to some but not all stressors, while elegant studies using immuno-neutralization of AVP also reported a blunted HPA response to a range of stressors including restraint, insulin-induced hypoglycemia and lipopolysaccharide." (PMID 33905792, 2021). "In mice, MLR-1023 increases insulin sensitivity, measured using the gold standard hyperinsulinemic euglycemic clamp test, and does not cause hypoglycemia." (PMID 34832978, 2021). "However, the incidence of hypoglycemia is also significantly increased in patients using insulin, and previous studies have shown that hypoglycemia is an independent predictor of hospitalization and one-year mortality in critically ill patients." (PMID 34335269, 2021). "CSII and ICT are associated with comparable metabolic control and treatment satisfaction but CSII was associated with lower insulin dosage and higher incidence of non-severe hypoglycaemia." (PMID 34301317, 2021). "There was 1 serious adverse event related to hypoglycemia, in an insulin-treated patient." (PMID 34158057, 2021). "The use of insulin pumps is associated with a reduction in HbA1c levels without an increased risk of hypoglycemia and seems to be more effective than multiple daily insulin injections." (PMID 33759789, 2021). "In contrast, islet parasympathetic innervation, inferred from pancreatic polypeptide secretion in response to insulin-induced hypoglycemia, appears intact in patients with T1D during the early stages of the disease and correlates with systemic epinephrine levels." (PMID 33753784, 2021). "Finally, insulin doses should be titrated daily and should also be tapered whenever glucocorticoid therapy is tapered in order to avoid hypoglycemia." (PMID 33920079, 2021). "Lower swelling ratio allowed for slow release of insulin without burst effect, so that insulin-iSFH injection did not cause hypoglycemia." (PMID 34307293, 2021). "In addition, annually, an estimated 100,000 emergency room visits and 30,000 hospitalizations are attributed to insulin, either due to hypoglycemia or errors in administration." (PMID 34458301, 2021). "When these systems are not able to prevent a hypoglycemic episode entirely, this diminution in delivered insulin may decrease the amount of carbohydrates (CHOs) required to treat hypoglycemia and the needless consumption of additional calories." (PMID 33535013, 2021). "Hypoglycemia risk was also lower for activities performed in the morning rather than in the afternoon, even with a 50% rapid-acting insulin reduction prior to later-day exercise." (PMID 34501920, 2021). "Our study also illustrated that insulin use in persons with compensated liver cirrhosis was associated with a higher risk of MACE, and these hazards persisted even after excluding persons with hypoglycemia." (PMID 34118892, 2021). "Episodes of hypoglycemia also remained unchanged over time among patients using insulin analogues." (PMID 33905628, 2021). "When hypoglycemia occurs, a hormonal response is induced by way of insulin secretion." (PMID 34067715, 2021). "This is a scenario specific to hypoglycemia, since other stimuli, including administration of amino acids, insulin withdrawal, lipopolysaccharide exposure and exercise lead to substantial glucagon responses though attenuated compared to nondiabetic individuals in head‐to‐head studies." (PMID 34405569, 2021).